DKK1 (dickkopf Wnt signaling pathway inhibitor 1)
Diseases named in the same sentence as DKK1 in open-access papers (continued):
Sharing a sentence is not in itself a finding about the gene and the disease.
Cognitive impairment (11 papers, 2013 to 2025). Abnormal cognition is characterized by deficits in thinking, reasoning, or remembering. "Fourth, induced Dkk1 expression in the adult mouse hippocampus leads to synapse loss, plasticity defects and cognitive impairment, features that can be reversed by cessation of Dkk1 expression." (PMID 35296808, 2022). "The mRNA level of DKK1 and the level of cognitive function showed a positive correlation and DKK1 was one of five risk factors involved in cognitive impairment of older people living in high fluorosis areas." (PMID 34886821, 2021). "In brief, our aim was to investigate the risk factors for cognitive disorders induced by high fluoride drinking water and the relationship between cognitive function and the expression of DKK1." (PMID 34886821, 2021). "In the CNS, Dkk-1 increases with age, inhibits neurogenesis and causes cognitive impairment." (PMID 35855111, 2022). "We sought to examine whether serum levels of Dickkopf-1 (Dkk-1), a Wnt antagonist, are associated with global disease progression in older adults with mild cognitive impairment (MCI) and mild-to-moderate AD." (PMID 31680933, 2019). "In AD brains there are an up-regulated expression of Dkk-1 compared to healthy individuals, while the chronic overexpression of Dkk-1 in transgenic mice causes an age-related tau phosphorylation and cognitive deficits." (PMID 24348327, 2013). "Notably, the Wnt antagonist Dkk1 induces AD-related synaptic loss and cognitive impairment." (PMID 31191253, 2019). "DKK1 reversed the improvement effect of OTN on cognitive impairment and neuronal damage in SAH rats." (PMID 38596082, 2024). "DKK1, an inhibitor of the canonical Wnt signalling pathway, has been reported to be involved in cognitive impairment." (PMID 34886821, 2021). "Inhibition of DKK1 has been shown to improve cognitive impairment and protect against neurotoxicity." (PMID 34836168, 2021). "In conclusion, cognitive impairment could be induced by high fluoride drinking water, and DKK1 may be involved in this process." (PMID 34886821, 2021). "Given the supporting evidence we presented previously, we propose that fasudil is able to protect against Aβ-induced cognitive impairment through its ability to antagonize an Aβ-activated Dkk1-Wnt-PCP-Daam1-RhoA/ROCK-dependent pathway that drives dendritic spine withdrawal and synapse loss." (PMID 29055813, 2018). "However, the difference of risk factors of cognitive impairment between induced by fluorosis and AD in older people were not clear, not to speak of whether DKK1 is involved in this disorder (cognitive impairment induced by fluoride)." (PMID 34886821, 2021).
lymph node metastasis (11 papers, 2012 to 2025). "Positive DKK1 staining was significantly associated with lymph node metastasis (P = 0.04)." (PMID 34117362, 2021). "There was a tendency that serum DKK1 is associated with lymph node metastasis (P = 0.058)." (PMID 31830954, 2019). "High DKK1 expression is correlated with advanced tumour stage, lymph node metastasis, and poor prognosis." (PMID 41477365, 2025). "Relative analysis showed a significant relationship between DKK1 positive expression and lymph node metastasis(P<0.05)." (PMID 24391982, 2013). "To determine which was the most suitable subtype of GIC for the high expression of DKK-1 and which test method had a greater impact on the prognosis, we conducted a network meta-analysis for TNM stage and lymph node metastasis." (PMID 33193872, 2020). "Serum DKK-1 levels correlated significantly with TNM stage (P = 0.009), tumor grade (P = 0.02), lymph node metastasis (P = 0.001), and expression of HER2 (P = 0.002)." (PMID 25116444, 2014). "DKK1 was also a prognostic factor for patients with earlier stage or no lymph node metastasis." (PMID 22649545, 2012). "DKK1 might be a valuable biomarker in predicting the prognosis of patients with earlier stage or no lymph node metastasis." (PMID 22649545, 2012). "Furthermore, in patients with no lymph node metastasis, the DFS and OS of DKK1 positive patients was significantly longer than that of DKK1 negative patients(DFS p = 0.002; OS p = 0.023)." (PMID 22649545, 2012).
intrahepatic cholangiocarcinoma (10 papers, 2013 to 2025). A carcinoma that arises from the intrahepatic bile duct epithelium in any site of the intrahepatic biliary tree. "Dickkopf‐1 (DKK1) is associated with poor prognosis in intrahepatic cholangiocarcinoma (iCCA), but the mechanisms behind this are unclear." (PMID 35924447, 2023). "DKK1 was also involved in the invasion and metastasis of intrahepatic cholangiocarcinoma (ICC) cells and lymph node metastasis." (PMID 34899842, 2021). "Nevertheless, DKK1 is not overly specific for HCC diagnosis, and a recent study reported that serum DKK1 was also elevated in patients with intrahepatic cholangiocarcinoma." (PMID 24252133, 2013). "Preclinical studies have demonstrated that DKK1-targeting agents, such as the monoclonal antibody DKN-01, exhibit promising antitumor effects in Wnt-driven malignancies, including esophageal, intrahepatic cholangiocarcinoma, and gallbladder cancer." (PMID 40565036, 2025). "Shi reported that tumor-expressed DKK1 is an independent prognostic factor for both RFS and OS, correlating to metastasis of hepatic hilar lymph nodes among intrahepatic cholangiocarcinoma (ICC)." (PMID 31830954, 2019).
medulloblastoma (10 papers, 2008 to 2025). A malignant, invasive embryonal neoplasm arising from the cerebellum. "ElasticNet coefficients highlighted the predictive importance of genes such as AXIN1, RNF43, STK3, LEF1, and DKK1 for identifying the WNT subtype status in this medulloblastoma validation cohort." (PMID 39851951, 2025). "Herein, the role of histone deacetylation was explored in these tumors, and it was found to contribute to the downregulation of the WNT inhibitor DKK1 in medulloblastoma." (PMID 37568705, 2023). "In fact, the use of the histone deacetylase inhibitor trichostatin A resulted in rescuing the expression of DKK1 and a subsequent increase in the apoptotic cell death of medulloblastoma cells." (PMID 37568705, 2023). "In accord with previous reports, we identified distinct groups of co-expressed genes that were highly enriched for WNT signalling in WNT medulloblastoma, (including DKK1, DKK2, DKK4, WIF1, LEF1 and WNT16)." (PMID 25412507, 2014). "Medulloblastoma is a heterogeneous pediatric brain tumor, and DKK-1 expression in primary medulloblastoma cells and patient samples by RT-PCR was found to be significantly down-regulated relative to normal cerebellum." (PMID 21029453, 2010). "In addition, adenoviral vector-mediated expression of DKK-1 in medulloblastoma cells significantly increases the apoptosis rate." (PMID 20920327, 2010). "A number of studies showed that DKK-1 induces apoptosis and inhibits tumor growth DKK-1 expression in primary medulloblastoma cells is significantly down-regulated relative to normal cerebellum and transfection of a DKK-1 gene construct into D283 cell line suppresses medulloblastoma tumor growth." (PMID 20920327, 2010). "Histone deacetylation silences Dickkopf WNT Signaling Pathway Inhibitor 1 (DKK1), which is an antagonist of the WNT signaling pathway and is important for medulloblastoma development." (PMID 34066495, 2021). "However, DKK1 (Dickkopf-1) is considered to be a negative regulator of WNT pathway, and has been implicated as a candidate gene that is epigenetically silenced in medulloblastoma, loss of which, may provide an avenue for WNT pathway activation with subsequent cell proliferation and survival." (PMID 31073965, 2019). "Transcripts contributing significantly to these enrichments encoded WNT16, DKK1 and LEF1 that are specifically over-expressed in WNT medulloblastoma irrespective of developmental control comparison." (PMID 25412507, 2014). "Transfection of a DKK-1 gene construct into D283 cell lines suppressed medulloblastoma tumor growth in colony focus assays by 60% (P < 0.001), and adenoviral vector-mediated expression of DKK-1 in medulloblastoma cells increased apoptosis fourfold (P < 0.001)." (PMID 21029453, 2010).
biliary tract cancer (9 papers, 2020 to 2024). "This mutational difference may be related to the difference in DKK-1 levels between biliary tract cancers." (PMID 33921232, 2021). "We conducted a single-arm, second-line phase II trial combining DKN-01, a humanized monoclonal antibody targeting Dickkopf-1 (DKK-1), and nivolumab to treat patients with advanced biliary tract cancer (NCT04057365)." (PMID 39417106, 2024). "The role of β-catenin and Dickkopf-1 (DKK1) is dependent on the specific immunobiology of T cell inflammation in biliary tract cancer (BTC)." (PMID 35121803, 2022). "Further experimental studies will be needed in the future and we would like to propose a prospective study on the diagnostic and prognostic efficacy of DKK-1 in CA 19-9 negative biliary tract cancer patients based on this study for clinical development." (PMID 33921232, 2021). "DKK1 expression together with CTNNB1 was found to worsen overall survival, as well as relapse-free survival, even in the presence of CD8+ tumor-infiltrating lymphocytes in biliary tract cancer." (PMID 39513892, 2024). "DKN-01, an anti-DKK1 mAb, could block the immunosuppressive effects of DKK1 in the tumor microenvironment (TME) and also perform potential antiangiogenic and immunomodulatory activity in combination therapy with gemcitabine/cisplatin in advanced biliary tract cancer." (PMID 34899842, 2021).
brain ischemia (9 papers, 2009 to 2025). Diminished or absent blood supply to the brain caused by obstruction (thrombosis or embolism) of an artery resulting in neurologic damage. "Increased expression of Dkk-1 is causally related to neurodegeneration processes in several central nervous system disorders other than AD, such as brain ischemia and temporal lobe epilepsy." (PMID 32850846, 2020). "DKK-1 has been implicated in cancer, brain ischemia, and bone disease; previous studies have shown a close association of serum levels of DKK-1 and atherosclerotic diseases such as premature myocardial infarction or ischemic cerebrovascular disease." (PMID 23359112, 2013). "In young transgenic mice (3 months-old), a trend was observed for lower levels of Dkk-1 in females than in males, suggesting a possible protective effect of female hormones, as has been previously reported in a model of cerebral ischemia and Dkk-1 expression." (PMID 39167347, 2024). "In cerebral ischemia (CI), it was discovered that elevated levels of DKK1 worsened the patient's condition by enhancing GSK-3β activity and obstructing the canonical Wnt pathway." (PMID 37780577, 2023). "Its homologue, Dickkopf-1 is a Wnt antagonist that contributes to neuronal apoptosis following brain ischemia; DKK1 has been described as a target for treatment in neurodegenerative disorders e.g. beta-amyloid deposition, epilepsy, excitotoxicity." (PMID 20509949, 2010). "This neuroprotective response is mediated by increase of Wnt3a and inhibition of Dkk1 elevation, triggered after cerebral ischemia." (PMID 19360103, 2009). "It was also found that 17β-estradiol downregulates Dkk-1 in a model of global cerebral ischemia." (PMID 39167347, 2024). "By preventing an increase in DKK1 levels, low physiological levels of E2 protect the hippocampal CA1 region against global cerebral ischemia." (PMID 37907850, 2023). "Moreover, induction of DKK‐1 was a key factor for the development of ischemic neuronal death, and blocking DKK‐1 could protect neurons against ischemic damage and decreased infarction volume in rat model with focal brain ischemia." (PMID 32324340, 2020).
hepatoblastoma (9 papers, 2010 to 2022). Hepatoblastoma (HB) is a malignant hepatic tumor and is the most common pediatric liver cancer. "DKK1 overexpression has been reported in hepatoblastoma, suggesting that DKK1 acts as an oncogenic factor through inhibition of the Wnt signaling pathway." (PMID 31568519, 2019). "DKK1 specifically has been shown to inhibit nephrogenic progression in the developing kidney and to accumulate in both WT and hepatoblastoma." (PMID 24481423, 2014). "Overexpression of DKK-1 has also been detected in human hepatoblastomas and Wilms' tumors." (PMID 21029453, 2010).
leukemia (9 papers, 2008 to 2022). A malignant (clonal) hematologic disorder, involving hematopoietic stem cells and characterized by the presence of primitive or atypical myeloid or lymphoid cells in the bone marrow and the blood. "Specifically, AML-exosomes, once taken up by stromal cells, induce the expression of DKK1, which suppressed normal hematopoiesis and promoted leukemia development." (PMID 35955960, 2022). "Both activation of (noncanonical) Wnt signaling by MSC-derived Wnt5a as well as inhibition of (canonical) Wnt-signaling by MSC-derived Dickkopf-related protein-1 (Dkk1) have been shown to decrease proliferation rates in two leukemia cell lines." (PMID 33287630, 2021). "Expression of Dkk1, an antagonist of wnt/β-catenin signaling in leukemia and MSCs was determined by quantitative real-time PCR (Q-PCR)." (PMID 28266575, 2017). "Here we show that cordycepin reduces CD34+CD38− cells in U937 and K562 cells and induces Dkk1 expression via autocrine and paracrine regulation in leukemia and mesenchymal stromal/stem cells (MSCs)." (PMID 28266575, 2017). "Hypermethylation of the CpG islands of the DKK1 promoter contributes to the absence of DKK1 expression in various tumors, including leukemia, and the DNA demethylating agent 5-aza-2-deoxycytidine reduces promoter methylation and restores DKK1 expression." (PMID 33420361, 2021).
neuroblastoma (9 papers, 2012 to 2025). Neuroblastoma (NB) is the most common solid, extracranial childhood tumor. "Nevertheless, the role and interlink between miR-335-3p and DKK1 in neuroblastoma cells have received minimal investigation." (PMID 40804038, 2025). "After coculture of SH‐SY‐5Y cells with overexpressing DKK1 or control HNSCC cells, neuritogenesis and commingling of neuroblastoma cells were increased in the DKK1‐overexpressing group." (PMID 38525111, 2024). "Taken together, the data suggest that reduction in DKK1 expression contributes to linc00467-mediated neuroblastoma cell survival." (PMID 24586304, 2014). "Similar to DKK3, DKK1 is also reported to be secreted in neuroblastoma cell lines, and downregulated indirectly by MYCN." (PMID 23226679, 2012). "To verify this hypothesis, we cocultured HNSCC and SH‐SY5Y neuroblastoma cells and found that DKK1 enhanced nerve cell migration." (PMID 38525111, 2024). "The migration abilities of neuroblastoma cells, which were enhanced by DKK1‐overexpressing HNSCC cell lines, could be reversed by an inhibitor of Akt (MK2206)." (PMID 38525111, 2024). "Similarly, the crucial role of factors blocking osteoblast differentiation, such as the Wnt pathway inhibitor, DKK-1, in bone invasion has been shown for neuroblastoma, another pediatric tumor with frequent bone metastases." (PMID 25714031, 2015). "While linc00467 had not been studied at all in the literature, we discovered that linc00467 suppressed the expression of its downstream protein-coding gene RD3, and induced neuroblastoma cell survival by reducing the expression of the tumour suppressor gene DKK1." (PMID 24586304, 2014). "Importantly, simultaneous knocking-down DKK1 expression blocks linc00467 siRNA-regulated neuroblastoma cell death." (PMID 24586304, 2014). "Importantly, knocking-down linc00467 expression with siRNA in neuroblastoma cells reduced the number of viable cells and increased the percentage of apoptotic cells, and co-transfection with DKK1 siRNA blocked the effects." (PMID 24586304, 2014). "The present study focused on DKK1, a negative regulator in the Wnt signaling pathway, as a key factor previously identified to be involved in the invasion and migration of colorectal, neuroblastoma and placental cells." (PMID 24137406, 2013). "Importantly, linc00467 enhances neuroblastoma cell survival through reducing DKK1 expression." (PMID 24586304, 2014). "To investigate the function of DKK1 in promoting PNI, we cocultured HNSCC and SH‐SY5Y neuroblastoma cells." (PMID 38525111, 2024). "In neuroblastoma, lncRNA Xist, which interacts with EZH2 to downregulate DKK1 by inducing H3 histone methylation, promotes neuroblastoma cell growth, proliferation, migration, and invasion via modulating H3 histone methylation of DKK1 in neuroblastoma." (PMID 34178980, 2021). "Only one study by Atmadibrata 42 reported that in neuroblastoma, N-Myc targeting LINC00467 could reduce the expression of tumour suppressor gene Dickkopf-related protein 1 (DKK1), thereby promoting neuroblastoma cell survival." (PMID 31772673, 2019).
postmenopausal osteoporosis (9 papers, 2013 to 2026). Metabolic disorder associated with fractures of the femoral neck, vertebrae, and distal forearm. "The main finding in our study was that cortical bone matrix contents of SOST and DKK1 in postmenopausal osteoporosis were positively associated with bone mass and strength." (PMID 31197079, 2019). "Previously, peers' studies have demonstrated the association of increased serum DKK1 level in postmenopausal osteoporosis and decreased bone mass." (PMID 28628652, 2017). "Modulation of DKK1 function through an experimental fully human anti-DKK1 antibody exhibited translational potential as a bone-anabolic agent for the treatment of human low bone mass disease, a characteristic of postmenopausal osteoporosis." (PMID 35355709, 2022). "Wnt-catenin signaling antagonists sclerostin and dickkopf-related protein-1 (Dkk-1) inhibit bone formation and are involved in the pathogenesis of postmenopausal osteoporosis (PO)." (PMID 34034718, 2021). "The past decade had witnessed frequent breaks in therapeutic development targeting LRP5 signaling, namely, the anti-DKK1 and anti-sclerostin molecules in the treatment of postmenopausal osteoporosis." (PMID 34796178, 2021). "This suggests that controlling DKK1 signaling using antisense oligonucleotides might be an alternative strategy in treating postmenopausal osteoporosis." (PMID 35355709, 2022). "Also, it suggests that pharmacologic inhibition of DKK-1 may have a therapeutic approach in postmenopausal osteoporosis." (PMID 23878759, 2013). "However, one study reported that bone DKK1 and SOST positively correlated with bone mineral density, microarchitecture, and strength in postmenopausal osteoporosis." (PMID 36768718, 2023). "The negative correlation between serum levels of DKK1 and alkaline phosphatase (an osteoblast product) is an indication that DKK1 plays a significant role in the biology of abnormal bone remodeling in postmenopausal osteoporosis." (PMID 23878759, 2013).